IL1B (interleukin 1 beta)
Diseases named in the same sentence as IL1B in open-access papers (continued):
Sharing a sentence is not in itself a finding about the gene and the disease.
prediabetes (27 papers, 2015 to 2025). "IR is a hallmark of prediabetes and can result from proinflammatory cytokines such as TNFα and IL1β causing impaired insulin signaling in insulin target organs." (PMID 26317345, 2015). "On the other hand, the gene expression of NLRP3, CASPASE-1, and IL-1β, as well as the serum IL-1β concentration, decreased significantly in the prediabetes exercise group after 6 months of combined Yijinjing and resistance training." (PMID 40761804, 2025). "The concentrations of proinflammatory molecules such as IL-6, IL-1β and IL-8 were increased in the T2D and prediabetes groups compared with the control group." (PMID 38834984, 2024). "In the prediabetes group, IL-1β, IL-6, IL-8, TNF-α and MAPK were significantly higher in those with Vit D insufficiency and deficiency groups." (PMID 38136648, 2023). "The present finding showed that serum Interleukin IL-2, IL-1β, and IL-1α levels of all prediabetes patients were increased when compared with healthy control cases (P < 0.05)." (PMID 37457235, 2023). "In prediabetes cases levels of cytokines: IL-2, IL-1β, and IL-1α were observed to be significantly higher than control group." (PMID 37457235, 2023). "Our findings showed that IL-1α, IL-1β and IL-2 were significantly elevated in individuals with prediabetes when compared with normal controls." (PMID 37457235, 2023). "For inflammatory biomarkers, IL-1β was significantly increased in prediabetes and T2DM compared to controls (p< 0.001)." (PMID 37383391, 2023). "In the CANTOS trial, an antibody inhibiting the action of IL-1β was able to reduce the incidence of CV events in a population largely composed by patients with T2D or prediabetes." (PMID 35503137, 2022). "Serum IFN-γ and IL-1β also showed a tendency toward increase in the patients with prediabetes compared with normal controls." (PMID 30867412, 2019). "Prediabetes was revealed by high glucose and HbA1C levels, which positively correlated with IL-1β; r = 0.52, P≤0.01 and r = 0.47, P≤0.022, respectively." (PMID 26930651, 2016). "The serum IL-1β concentration was higher in the prediabetes control group than in control subjects." (PMID 40761804, 2025). "Additionally, the prediabetes and T2D groups had higher concentrations of proinflammatory molecules such as IL-6, IL-1β and IL-8, and lower concentrations of IL-10, an anti-inflammatory cytokine, than controls (P < 0.001)." (PMID 38834984, 2024). "Inhibition of IL-1β leads to a decrease in the inflammatory process in pancreatic islets, and a reduction in glucose levels which results in an improvement of vascular complications and prevents the conversion of prediabetes to clinically expressed T2DM." (PMID 38962295, 2024). "However, the levels of the proinflammatory interleukins IL-6, IL-1b and IL-8 were increased in the T2D and prediabetes groups compared with the control group." (PMID 38834984, 2024). "Moreover, immunohistochemical staining revealed that a higher concentration of TNF-α and IL-1β was present in the IMAT cells of prediabetes rats compared to the control group." (PMID 37899436, 2023). "miR-192 was up-regulated in obese prediabetes and targeted PIK3R4, ACVR2B, and inflammatory mediators such as TNFα and IL-1β." (PMID 41400625, 2025). "A significant overactivation of the inflammasome was observed in the prediabetes control group compared to healthy control subjects, as indicated by the results obtained through NLRP3, caspase-1, and IL-1β protein concentrations." (PMID 40761804, 2025). "Similar analysis in Indians showed significantly higher levels of inflammatory biomarkers like high-sensitive C-reactive protein (hsCRP), IL1β, IL13, IL17A, IL6, TNFα, and IAP in individuals with prediabetes compared to normoglycemic individuals." (PMID 33658065, 2021). "Cytokines play an important role in the procedure of β-cell failure and IL-1β; TNF-α and IL-6 have been shown to diversely regulate pancreatic β-cell function leading to inflammation in prediabetes patients." (PMID 30039349, 2019).
prediabetes (continued). "Research indicates that individuals with prediabetes exhibit elevated levels of multiple inflammatory markers, including resistin, interleukin-6 (IL-6), TNF-α, interleukin-1β (IL-1β), and monocyte chemoattractant protein-1 (MCP-1), in their serum along with high fasting blood glucose levels." (PMID 39634176, 2024). "For this purpose, we assessed the relationship between serum Vit D levels and acute phase reactants such as CRP, fibrinogen and ferritin and pro-inflammatory markers such as IL-1β, IL-6, IL-8, TNF-α, NF-κB and MAPK in newly diagnosed prediabetes and type 2 DM patients." (PMID 38136648, 2023). "In another study conducted in middle-aged overweight or obese men with prediabetes, they evaluated the effect of a low-volume HIIT training program with different levels of compression, with or without berberine supplementation, on the upregulation of NLRP3 and IL-1β non-coding RNA." (PMID 40761804, 2025). "However, such an approach, i.e., targeting the IL-1 pathway, and in particular IL-1β, is not effective in reducing the progression of prediabetes to frank T2D." (PMID 39404426, 2024). "In LOsG-induced prediabetes, although pancreatic ROS stress remained high on LOsG treatment day 38, there were no alterations in mRNA levels of ER stress (XBP1 and BIP), inflammation (IL6 and IL1β), and hypoxia-responsive (HIF1α and GAPDH) genes between LOsG- and sham-treated groups." (PMID 30975975, 2019). "IL1-β, IL-6, IL-8, TNF-α, NF-κB, and MAPK were also significantly increased in the T2D and prediabetes groups compared to non-diabetic groups, indicating their role as pro-inflammatory factors." (PMID 39568808, 2024). "This study revealed that the IL1-β, IL-6, IL-8, TNF-α, NF-κB and MAPK levels as pro-inflammatory markers and CRP, fibrinogen and ferritin as serum acute phase reactants were significantly increased in the prediabetes and T2DM groups compared to nondiabetes group." (PMID 38136648, 2023).
Splenomegaly (27 papers, 2013 to 2026). Abnormal increased size of the spleen. "By contrast, we recently documented that IL1B rs16944 polymorphism was associated with the reduced risk of splenomegaly, suggesting that it has a protective role against the activation of the reticuloendothelial system in cCMV." (PMID 34578364, 2021). "In relation to reticuloendothelial system abnormalities, IL1B rs19944 polymorphism was associated with the reduced risk of splenomegaly (OR = 0.36, 95%CI, 0.14–0.98; p = 0.034) in log-additive model." (PMID 32421725, 2020). "Next, we observed the association between polymorphism of IL1B rs16944 and the reduced risk of splenomegaly." (PMID 32421725, 2020). "In these studies, deficiency for IL-1β or IL-1R1 attenuated bone marrow fibrosis and splenomegaly." (PMID 41298546, 2025). "However, Pg induced weight loss and systemic inflammation, such as splenomegaly and increased IL‐1β and TNF‐α levels in plasma, whereas Pg OMVs had minimal impact." (PMID 39932228, 2025). "FMF-KI mice exhibit dysregulated macrophage activation and IL-1β over-production, which serves to create a pro-inflammatory milieu that drives continuous neutrophil recruitment into inflamed tissues, causing splenomegaly, joint swelling, peritonitis, and hair loss." (PMID 36494621, 2022). "In relation to particular symptoms, polymorphism of IL12B rs3212227 was linked to decreased risk of prematurity (OR = 0.37;95%CI,0.14–0.98;p = 0.025), while polymorphism of IL1B rs16944 was linked to reduced risk of splenomegaly (OR = 0.36;95%CI,0.14–0.98; p = 0.034) in infants with cCMV infection." (PMID 32421725, 2020). "Neutralization of IL-1α, and to a much lesser extent IL-1β, was associated with a significant increase in the mortality of R. typhi-, R. rickettsii-, and R. montanensis-infected mice and resulted in the development of splenomegaly, which correlated with an increase in bacterial loads in the spleen." (PMID 35130729, 2022). "Interestingly, all these findings cumulatively suggest that IL1B rs16944 polymorphism may promote cCMV infection, while simultaneously reducing the risk of splenomegaly and CNS damage." (PMID 34578364, 2021). "PLO treatment also mitigated IMQ-induced splenomegaly, and suppressed IL-1b and IL-6 expression in the spleen, and reduced IL-6 expression in the axillary lymph nodes." (PMID 42306466, 2026). "Our patient’s clinical picture, recurrent fever, mild splenomegaly, systemic inflammation, and elevated proinflammatory markers (IL-1β, IL-6, serum amyloid A), aligns with the phenotype of patients exhibiting complete loss of DOCK11 expression." (PMID 41250716, 2025). "The increase of IL-1β and IL-6 is consistent with a systemic inflammatory trigger preceding the phenotypes described earlier (UD and splenomegaly)." (PMID 37400834, 2023). "We found that innate susceptibility to stress correlates with chronic inflammation, development of splenomegaly and a significant increase in the levels of circulating pro-inflammatory cytokines IL-1β and IL-6." (PMID 31707362, 2019). "Our study extended previous findings by showing that splenomegaly and elevated serum levels of IL-1β and TNF-α in LPS models could be rescued by PDA NPs treatment." (PMID 36765377, 2023). "We observed a dramatic increase in the expression of several proinflammatory markers such as Il17a, Ifnγ, Tnfα, IL-1β and Ifitm1, and chemokines such as Ccl1, Cxcl10, Ccl22 and Xcl1, in ATMINΔLNBS1ΔL mice displaying splenomegaly, compared to the other genotypes." (PMID 26544571, 2015). "In another study, the inhibition of TNF-α, IL-1β, and IL-6 overexpression by CLX in spleen tissues, suppressed splenomegaly, contributed to the development of liver cirrhosis." (PMID 35884918, 2022).
Splenomegaly (continued). "However, our new method leads to considerably reduced systemic inflammatory reactions in the animals, as indicated by the moderate splenomegaly and weight loss, as well as little or no significant increase of IL-1β, TNF-α and IFN-α concentrations in the blood of the animals." (PMID 30842501, 2019). "Therefore, we examined the serum levels of the pro-inflammatory cytokines IL-1β, IL-6, and TNF-α in NCI-H460 xenograft model, which has the best response to GLPs in terms of tumor and splenomegaly inhibition." (PMID 36185644, 2022). "Moreover, transfer of Il-1α−/− BMDMs resulted in the development of splenomegaly and an increase in bacterial burden in the spleens of Cl2MBP-treated WT mice, which correlated with a decrease in IL-1α serum concentrations without affecting IL-1β serum levels." (PMID 35130729, 2022). "Inflammation-mediated splenomegaly of C26-mice was inhibited by PM01183 for as long as the treatment lasted, without reducing IL-6, M-CSF or IL-1β in plasma." (PMID 32824440, 2020).
allergic rhinitis (26 papers, 2008 to 2025). Inflammation of the nasal mucous membranes caused by an IgE-mediated response to external allergens. "Both IL-1β and IL-17, seem to be involved in the pathogenesis of allergic rhinitis, and these two signalling pathways can be associated." (PMID 36203607, 2022). "After multivariate analysis, only paternal allergic rhinitis (6.4-fold increase in risk) and high expression of IL-1β (4.7-fold increase in risk), emerged as significant risk factors of moderate to severe PAR (p = 0.011 and p = 0.030, respectively)." (PMID 31548841, 2019). "Multivariate analysis showed only paternal allergic rhinitis and high expression of IL-1β as significant risk factors of moderate to severe PAR with 6.4 fold and 4.7 fold-increase in risk, respectively (p = 0.011 and p = 0.030)." (PMID 31548841, 2019). "Moreover, paternal allergic rhinitis and high expression of IL-1β were the risk factors for moderate to severe AR (6.4-fold and 4.7-fold increase in risk, respectively), and promoted the inflammation processes." (PMID 36203607, 2022). "The study involved molecular docking analysis of berberine with five key genes (Alb, Il6, Il1b, Tlr4, and Ptgs2) to validate its potential targets against allergic rhinitis." (PMID 38796469, 2024). "The inhibitory effects of TQ on IL-4 production, OVA-specific IgE, TNF-α and IL-1b gene expression, edema, and eosinophil infiltration in the nasal mucosa were reported in a rat model of allergic rhinitis." (PMID 33859710, 2021). "Our nested case–control study demonstrated that elevated IL-1β levels and paternal allergic rhinitis have a significant effect on the severity of AR." (PMID 31548841, 2019). "In contrast, low constitutive B1R expression is upregulated in human nasal epithelial cells in allergic rhinitis subjects compared to controls and in human primary bronchial epithelial cells post stimulation with IL-1β and TNF-α." (PMID 24475248, 2014). "Activation of kinin receptors may underlie production of chemokines in several models of inflammation, including response to the cytokine IL-1β in mesenteric venules, inflammatory pain, and allergic rhinitis." (PMID 18986535, 2008). "Furthermore, the MCODE plugin was employed to pinpoint 14 genes (Cyba, Nfkbia, Fos, Mpo, Il6, Il1b, Sele, Vcam1, F2, Tlr4, Alb, Egr1, Smad3, and Ptgs2) forming a primary cluster, potentially representing a crucial regulatory network for berberine in treating allergic rhinitis." (PMID 38796469, 2024). "A recent study using the iron chelator, di-2-pyridylketone-4,4-dimethyl-3-thiosemicarbazone, identified a dose-dependent reduction in serum levels of IL-1β and TNF-α in a murine model of allergic rhinitis." (PMID 32466384, 2020). "The targets of 48 putative therapeutic components in the treatment of allergic rhinitis include IL6, TNF, CXCL8, ICAM1, ILA, MMP9, IL10, and IL1B." (PMID 31611923, 2019). "Data from their experiments showed decreased pro-caspase-1, pro-IL-1β, and ASC mRNA levels in both asthmatic patients and patients with allergic rhinitis." (PMID 26091108, 2015). "These outcomes support the findings in rats with allergic rhinitis, further proving that APS inhibits the activation of NLRP3 inflammatory vesicles in rats, hence lowering the production of inflammatory markers (Caspase-1, IL-1β, and ASC)." (PMID 40427385, 2025). "Supplementation with baicalin in the diet reduced the serum concentrations of IgE, IL-1β, IL-4, IL-6, TNF-α, and histamine in rats with allergic rhinitis, which suggests its potential as a therapeutic agent for allergic rhinitis through inhibition of inflammation mediators." (PMID 41463802, 2025). "Furthermore, berberine (50 or 100 mg/kg) suppressed TNF-α, IL-6, IL-1β, IL-17, and IgE levels in the OVA-induced allergic rhinitis group (p < 0.01)." (PMID 38796469, 2024).
allergic rhinitis (continued). "The combined blockade of IL-1β and TNF-α by the intranasal instillation of 0.1% anti-IL-1β/TNF-α IgY could be a potential alternative strategy for preventing and treating allergic rhinitis." (PMID 27046957, 2016). "This study aims to determine whether the combined blockade of IL-1β and TNF-α can alleviate the pathological allergic inflammatory reaction in the nasal mucosa and lung tissues in allergic rhinitis (AR) guinea pigs." (PMID 27046957, 2016). "α-Pinene, the main component of SO, decreased TNF-α, IL-1β, IL-6, intercellular adhesion molecule-1 (ICAM), and macrophage inflammatory protein-2 (MIP-2) levels, as well as eosinophil and mast cell infiltration in the nasal mucosa in an ovalbumin-sensitized allergic rhinitis mouse model." (PMID 35744988, 2022).
bladder cancer (26 papers, 2011 to 2025). "IL-6 and IL-1b are proinflammatory cytokines that have been linked to bladder cancer progression." (PMID 37901214, 2023). "The anti-proliferative and pro-apoptotic effects of EVSs derived from UMSC were detected in bladder carcinoma.There are some reports suggested that IL-1β blockade may be a preventive strategy for high risk individuals." (PMID 38105218, 2023). "IL-6 and IL-1β play a certain role in inflammatory stress caused by clinical infection and the immune regulation of patients and are known to possess positive clinical significance in the postoperative tissue trauma repair of bladder cancer." (PMID 35531475, 2022). "In bladder cancer patients’ samples, IL-1β is highly expressed and induces the urokinase-type plasminogen activator receptor and MMP9 expression by activating the MAPK and NF-κB pathways, thus promoting bladder cancer cell invasion." (PMID 39858071, 2025). "Elevated levels of IL-1β are observed in many cancers, including colorectal, lung, breast, prostate, ovary, pancreas, and bladder cancer." (PMID 39275392, 2024). "In previous research, we showed that IL-1β induces the upregulation of AP-1 signaling in bladder cancer cell lines." (PMID 38671854, 2024). "Specifically in BLCA, CAF promotes the Wnt signaling pathway in bladder cancer cells through paracrine IL1β, thereby enhancing their proliferation and invasion." (PMID 37124542, 2023). "The only earlier published results of MSC effects on 5637 and HT-1376 bladder cancer cell lines by ELISA reported cell line-dependent effects on IL-1B, IL-6, IL-8, TNFα, GM-CSF, MCP-1, TGF-β, and RANTES." (PMID 37781195, 2023). "In this study, we investigated the effect of EGCG on interleukin (IL)-1β-induced cell invasion and uPAR activity in T24 human bladder cancer cells." (PMID 36430487, 2022). "Our results demonstrate that EGCG inhibits IL-1β-induced uPAR expression by inhibiting ROS production and AP-1/NF-κB activation, and by decreasing cell invasion in T24 bladder cancer cells." (PMID 36430487, 2022). "In the current work, we describe the mechanism of action of EGCG in T24 bladder cancer cells under the presence of IL-1β, which is demonstrated to inhibit tumor proliferation and uPAR upregulation." (PMID 36430487, 2022). "In this study, GEPIA2 and TIMER2.0 results showed significantly increased IL-1β and uPAR expression in bladder cancer subjects." (PMID 36430487, 2022). "Our findings support a similar mechanism of EGCG suppressing IL-1β-induced NF-κB and AP-1 in T24 bladder cancer cells, along with a delay in IκBα and c-Jun degradation." (PMID 36430487, 2022). "In summary, IL-1β induces uPAR expression and activates the NF-κB/AP-1/MAPKs signaling pathways, which lead to bladder cancer progression, invasion, and metastasis." (PMID 36430487, 2022). "To evaluate the potential interplay between IL1RA and IL1B in the context of bladder cancer cell invasion, we first identified the release of sIL1RA in the supernatant of RT4 and UROtsa cells (endogenous IL1RA) as well as of T24-IL1RA (ectopic IL1RA)." (PMID 34070905, 2021). "BCG also induced a strong release of IFN‐γ, TNF‐α, IL‐1β, IL‐10, and IL‐12p70 in human bladder cancer cells." (PMID 30358081, 2019). "We found a decreased interleukin (IL)-1β concentration in irradiated wild-type MB49 bladder cancer cells of the culture medium." (PMID 31766169, 2019). "The significance of this IL-1β dependent increase in AKR1C1 was confirmed in clinical specimens of human bladder cancer tissues." (PMID 27698389, 2016). "IL-1β enhanced the expression of AKR1C1 in the three bladder cancer cell lines, UM-UC-3, TCC-SUP, and 5637 cells." (PMID 27698389, 2016). "The results allow us to formulate a preliminary hypothesis that HIF-1α, ANG-2, and IL-1β may be biomarkers characteristic of bladder cancer, having elevated concentrations in patients with that disease." (PMID 39275392, 2024). "The gene expression of PLAUR and IL-1β is shown in bladder carcinoma." (PMID 36430487, 2022).